LRP6 (LDL receptor related protein 6)
Diseases named in the same sentence as LRP6 in open-access papers (continued):
Sharing a sentence is not in itself a finding about the gene and the disease.
cleft lip (2 papers, 2019 to 2023). Congenital defect in the upper lip where the maxillary prominence fails to merge with the merged medial nasal prominences. "Recently, more attention has been attracted to studying the relationship between LRP6 and tooth/craniofacial development owing to several case reports about tooth agenesis and cleft lip caused by mutations in the LRP6 gene." (PMID 36694134, 2023). "Lrp6 deprivation causes a cleft lip with cleft palate in mice and Lrp6-mediated Wnt/β-catenin signaling controls the formation and fusion of facial primordia." (PMID 31492028, 2019).
diabetic nephropathy (2 papers, 2011 to 2017). "We assessed tag and potentially functional single nucleotide polymorphisms (SNPs; n = 31) in four key Wnt pathway genes (CTNNB1, AXIN2, LRP5 and LRP6) for association with diabetic nephropathy using a case-control design." (PMID 21876774, 2011). "Our results suggest that analysed common variants in CTNNB1, AXIN2, LRP5 and LRP6 are not strongly associated with diabetic nephropathy in type 1 diabetes among white individuals." (PMID 21876774, 2011). "In diabetic nephropathy, the activation of Wnt signaling in mesangial cells by CCN2 was along with stimulated phosphorylation of LRP6, nuclear localization of β-catenin, and expression of Wnt targets." (PMID 28870205, 2017). "Three additional SNPs (rs2075241 in LRP6; rs3736228 and rs491347 both in LRP5) were marginally associated with diabetic nephropathy, but none of the associations were replicated in an independent dataset." (PMID 21876774, 2011).
ectodermal dysplasia (2 papers, 2022 to 2025). "Here, we report a novel LRP6 C1032F mutation in one ectodermal dysplasia family, highlighting YWTD-motif targeting as a generalized mechanism in LRP6-associated tooth agenesis and involvement of second-hit modifier mutations in LRP6-associated clinical heterogeneity." (PMID 40687612, 2025). "A newly reported ectodermal dysplasia, linked to the gene LRP6, is described here in more detail." (PMID 36553593, 2022).
esophageal cancer (2 papers, 2019 to 2023). A primary or metastatic malignant neoplasm involving the esophagus. "The results showed a significant correlation between the expression levels of SPINK5 and β‐catenin (CTNNB1), LRP5, LRP6, DVL3, LEF1, AXIN2, MYC, and cyclin D1 (CCND1) in esophageal cancer." (PMID 30868765, 2019).
kidney stones (2 papers, 2022 to 2025). "In a study on calcium oxalate (CaOx) kidney stones, it is speculated that CaOx promotes kidney stone formation by downregulating the Cav-1 and low density lipoprotein receptro-related protein 6 (LRP6)/Wnt/β-catenin pathways, causing autophagy dependent ferroptosis." (PMID 41030451, 2025). "We presumed that CAV1 could promote Wnt/β-catenin signaling pathway through up-regulating LRP6, then LRP6/WNT suppressed ferroptosis via alleviating autophagy of epithelium and finally decreased kidney stones formation." (PMID 36128191, 2022).
liver fibrosis (2 papers, 2024 to 2025). "Rats fed an ethanol-containing Lieber-DeCarli diet to induce liver fibrosis and model early-stage ALD were then administered FMT from healthy rats or treated with LRP6-CRISPR." (PMID 38322428, 2024).
lung adenocarcinoma (2 papers, 2018 to 2021). A carcinoma that arises from the lung and is characterized by the presence of malignant glandular epithelial cells. "We tested an alternative lung adenocarcinoma cell line, H3122, and inhibiting MET with Crizotinib reduced mature LRP6, an effect that was almost abolished when ZNRF3/RNF43 where siRNA-inhibited." (PMID 34590584, 2021).
metastatic cancer (2 papers, 2022 to 2024). A carcinoma which has spread from the original site of growth to another anatomic site. "LRP6 is detected in different tissue types and is involved in numerous biological activities such as cell proliferation, specification, metastatic cancer, and embryonic development." (PMID 35052459, 2022).
metastatic disease (2 papers, 2013 to 2021). "LRP6 expression is significantly up-regulated in prostate patients with metastatic disease compared to those without metastasis, and is associated with a significantly increased risk of recurrent disease." (PMID 23469146, 2013).
metastatic prostate carcinoma (2 papers, 2023 to 2025). A carcinoma that arises from the prostate gland and has spread to other anatomic sites. "In the univariate analysis, several factors, namely T stage, GS, LRP6, and LRRK2, demonstrated strong associations with metastatic prostate cancer." (PMID 40660132, 2025). "Several gene mutations, including PIK3CA, LRP6, LRRK2, and BRCA2, were found to be associated with metastatic prostate cancer and BCR." (PMID 40660132, 2025). "Subsequently, the multivariate analysis, focusing on these previously identified significant factors, confirmed T stage, GS, LRP6, LRRK2, PIK3CA, and APOBEC3B deletion as significant predictors of metastatic prostate cancer." (PMID 40660132, 2025). "Key predictors of metastatic prostate cancer identified were T stage, GS, PIK3CA, LRP6, LRRK2, and APOBEC3B deletion." (PMID 40660132, 2025).
multiple myeloma (2 papers, 2023 to 2025). "We show that anti‐LRP6 could be of therapeutic benefit to prevent myeloma‐induced bone loss, but superior protection against bone loss and reduced strength was demonstrated when used in combination with anti‐DKK1." (PMID 36987921, 2023). "Using a genetic strategy, our group has discovered that GRP94 is an essential chaperone for folding the Wnt co-receptor LRP6 and that it is required for multiple myeloma cell survival, which is mediated in part by the Wnt target survivin." (PMID 41296387, 2025). "Nonetheless, the combination of anti‐LRP6 and anti‐DKK1 antibodies provided superior protection against myeloma‐induced bone loss, as well as providing superior protection against myeloma‐induced vertebral fracture compared to the single treatment approach." (PMID 36987921, 2023). "Overall, these results demonstrate that anti‐LRP6 antibody prevents exacerbated myeloma‐induced bone resorption." (PMID 36987921, 2023). "To address this, we examined the impact of a novel anti‐LRP6 antibody that potentiates LRP6‐mediated Wnt1 class signaling in normal and myeloma‐burdened bone conditions." (PMID 36987921, 2023). "Overall, this is the first study to define the cellular mechanisms driving improvements in bone volume in both naïve and myeloma‐bearing mice treated with the novel LRP6 receptor targeting antibody, anti‐LRP6." (PMID 36987921, 2023). "One aspect we did not explore was circulating levels of DKK1 and SOST in both naïve and myeloma‐bearing conditions, and the influence of either single or combination strategies with anti‐LRP6 and anti‐DKK1 on these antagonists." (PMID 36987921, 2023). "We treated both naïve (non‐tumor‐bearing) mice and mice bearing murine 5TGM1 myeloma cells with anti‐LRP6 antibody twice weekly and measured bone structural changes by μCT analysis." (PMID 36987921, 2023). "Although the reduction at the extraskeletal site with anti‐LRP6 alone requires further exploration, these data support the safe use of anti‐LRP6 alone or in combination with anti‐DKK1 to treat patients with myeloma." (PMID 36987921, 2023).
neural tube defect (2 papers, 2021 to 2023). A congenital defect characterized by failure of the neural tube to close completely; this results in the presence of openings in the brain or spinal cord. "Previous studies have reported the significant association of LRP6 pathogenic variants with congenital neural tube defects and congenital tooth agenesis." (PMID 36902838, 2023). "The P1427Q mutation is located in the intracellular domain near the phosphorylation motif of LRP6 and was identified in the Chinese Han Population with neural tube defects (NTD) and induced over-active Wnt/β-catenin signaling." (PMID 33391533, 2021).
non-small cell lung carcinoma (2 papers, 2012 to 2025). A group of at least three distinct histological types of lung cancer, including non-small cell squamous cell carcinoma, adenocarcinoma, and large cell carcinoma. "For example, NINJ1 has been shown to promote the formation and progression of non-small cell lung cancer (NSCLC) by protecting cancer stem cells from hostile microenvironments via the ligand-independent activation of the LRP6/β-catenin signaling pathway." (PMID 40075648, 2025). "Endogenous Wnt3a and LRP6 levels were assessed in seven non-small cell lung cancer cell lines (A549, H322, H596, H460, H358, H2009, and H1299) by western blot analysis." (PMID 22606268, 2012).
pancreatic ductal adenocarcinoma (2 papers, 2018 to 2020). An infiltrating adenocarcinoma that arises from the epithelial cells of the pancreas. "Inhibition of LRP6 by miRNA‐454 in pancreatic ductal adenocarcinoma exerted antiangiogenic and antimetastatic effects." (PMID 30411539, 2018). "miR-454 suppresses the growth, angiogenesis and metastasis of pancreatic ductal adenocarcinoma by targeting SDF-1 and LRP6." (PMID 32536825, 2020).
prion disease (2 papers, 2016 to 2017). A transmissible disease that is caused by a protein that is able to induce abnormal folding of normal cellular proteins, leading to characteristic spongiform brain changes, which are associated with neuronal loss without an inflammatory response. "In line with our previous study, the glycosylated form of LRP6 disappeared in the 263K infected group might be a potential reason to the downregulation of REST in prion disease." (PMID 28515679, 2017). "Collectively, we demonstrate for the first time novel neuroprotective function of REST in prion diseases and hypothesise that the LRP6-Wnt-β-catenin/REST signaling plays critical and collaborative roles in neuroprotection." (PMID 26919115, 2016).
Stroke (2 papers, 2022). Sudden impairment of blood flow to a part of the brain due to occlusion or rupture of an artery to the brain. "Likewise, LRP6 haploinsufficiency increases proinflammatory markers, mitochondrial dysfunction, and stroke volume." (PMID 35419167, 2022).
taurodontism (2 papers, 2021 to 2026). Taurodontism is a dental anomaly characterized by an elongated pulp chamber, displaced toward the apical floor of the tooth with no constriction at the level of the cemento-enamel junction, and short roots. "In Family 9 the proband showed agenesis of 15 permanent teeth and taurodontism caused by the heterozygous LRP6 defect c.1003 C > T, p.(Arg335*)." (PMID 34593752, 2021).
attention deficit-hyperactivity disorder (1 paper, 2024). A disorder characterized by a marked pattern of inattention and/or hyperactivity-impulsivity that is inconsistent with developmental level and clearly interferes with functioning in at least two settings (e.g. at home and at school). "Impairment in the Wnt pathway has been associated with various psychiatric disorders in humans, such as WNT1, WNT2, and WNT7A in autism spectrum disorder, WNT7B and LRP5 in SCZ, and LRP5 and LRP6 in attention-deficit/hyperactivity disorder." (PMID 39452096, 2024).
autism (1 paper, 2025). Persistent deficits in social interaction and communication and interaction as well as a markedly restricted repertoire of activity and interest as well as repetitive patterns of behavior. "In turn, the loss of PRG3 disrupts the Wnt/β-catenin signaling pathway in NPCs by affecting their receptor low-density lipoprotein receptor-related protein 6 (LRP6), leading to abnormal neuronal development and autism-like behaviors later in life." (PMID 40260079, 2025).
Barrett esophagus (1 paper, 2019). Esophageal lesion lined with columnar metaplastic epithelium which is flat or villiform. "We demonstrated for the first time a comprehensive analysis of all 10 frizzled receptors and their co-receptors LRP5 and LRP6 in an in vitro cell culture model of Barrett’s esophagus and in primary human specimens from normal squamous epithelium, Barrett’s mucosa, HGIN, and EAC." (PMID 30841855, 2019).
bone sarcoma (1 paper, 2015). A sarcoma that arises from the bone. "LRP6, LRP8 and Ror2 levels were significantly higher in bone sarcoma cells than in hMSC, while LRP5 levels were decreased in bone sarcoma cells." (PMID 25999350, 2015).
Chronic Heart Failure (1 paper, 2021). "This study aims to explore the association between common variants of LRP6 and the prognosis of chronic heart failure (CHF) patients." (PMID 35187114, 2021).
colorectal adenoma (1 paper, 2014). An adenoma that arises from the colon or rectum. "Additionally, in human colorectal adenoma and carcinoma cells, PGE2 treatment up-regulated the protein expression of the Wnt target gene, leucine-rich G-protein coupled receptor 5 (LGR5), which internalizes FZD co-receptor LRP6 and decreases Wnt activity." (PMID 24656144, 2014).
coronary artery disease, autosomal dominant 2 (1 paper, 2022). Any coronary artery disease in which the cause of the disease is a mutation in the LRP6 gene. "Mutations in the LRP6 gene (located on chromosome 12p13.2) encoding low-density lipoprotein receptor-related protein 6 (LRP6) cause Coronary artery disease, autosomal dominant, 2 (ADCAD2) (OMIM, 610,947)." (PMID 35743896, 2022).
cortical dysplasia (1 paper, 2023). "SFRP1, LRP6, FZD4 and CTNNBIP1 genes showed very similar percentage delta CT values in control tissue and NAAC and with a difference in these delta values in tissue with cortical dysplasia." (PMID 37749503, 2023).
cyst (1 paper, 2011). A sac-like closed membranous structure that may be empty or contain fluid or amorphous material. "Moreover, active LRP6 was homogenously distributed in the grey matter, although was also observed in several cells around the wound epicentre at 24 hpi, and it was even more prominent in the cells surrounding the cyst and in the grey matter from 7 dpi." (PMID 22073235, 2011).
diabetic retinopathy (1 paper, 2014). "Interestingly, SERPINA3 K, which acts as a Wnt signaling inhibitor by binding to LRP 6, reduced diabetic retinopathy." (PMID 25232946, 2014).
endotoxemia (1 paper, 2021). "The immunofluorescence intensities of p-Lrp6 and β-catenin were elevated and that of Axin was reduced during endotoxemia, which were suppressed by Wnt-C59." (PMID 34200709, 2021).
Ewing sarcoma (1 paper, 2019). A small round cell tumor that lacks morphologic, immunohistochemical, and electron microscopic evidence of neuroectodermal differentiation. "In this study, we showed that APCDD1 knockdown increased the expression of CDC25A, LRP6, LEF1 and NKD1, which are confirmed targets of the canonical Wnt pathway in Ewing sarcoma, implying that APCDD1 might act as a Wnt inhibitor in this cancer." (PMID 30496486, 2019).
fibrosarcoma (1 paper, 2017). A malignant mesenchymal fibroblastic neoplasm affecting the soft tissue and bone. "LRP6 facilitates oncogenesis by mediating Wnt/β-catenin subcellular localization in fibrosarcoma." (PMID 29108281, 2017).
heart failure (1 paper, 2021). Inability of the heart to pump blood at an adequate rate to meet tissue metabolic requirements. "LRP6 may serve as a novel therapeutic target for abrogating maladaptive cardiac remodeling and heart failure." (PMID 33391533, 2021).
ischemic disease (1 paper, 2025). Lack of blood supply to an area of the body, resulting in impairment of tissue oxygenation. "LRP6 belongs to the low density lipoprotein receptor superfamily and engages in regulating various disease processes, including ischemic diseases." (PMID 40709490, 2025).
kidney cancer (1 paper, 2024). Primary or metastatic malignant neoplasm involving the kidney. "To explore the mechanisms by which LRP6 may regulate the development of kidney cancer, we first analysed differential gene expression in samples with differential LRP6 expression using TCGA kidney clear cell carcinoma samples, and in total we identified 9 up-regulated and 739 down-regulated genes." (PMID 38226972, 2024).
lung squamous cell carcinoma (1 paper, 2019). "These polymorphisms were also found associated with a reduced risk of lung squamous cell carcinoma (SCC) where LRP6 rs6488507 synergistically increased the risk of NSCLS in tobacco smokers in Chinese populations." (PMID 31031810, 2019).
migraine (1 paper, 2022). "Therefore, as proposed for AD, Wnt activators that restore Wnt/β-catenin signalling in brain, particularly those targeting Wnt antagonist DKK1 and Wnt receptor LRP6, could represent novel therapeutic tools for migraine treatment." (PMID 35546551, 2022).
nasal polyp (1 paper, 2012). "Notably, we found that the genes involved in the Wnt pathway were enriched (P = 0.026), and four genes (FZD5, LRP6, PPP2R1B, and TBL1XR1) in this pathway switched to proximal APA sites in nasal polyp tissue." (PMID 23185289, 2012).
nasopharyngeal carcinoma (1 paper, 2025). A carcinoma arising from the nasopharyngeal epithelium. "Conversely, in nasopharyngeal carcinoma (NPC) PEDF expression suppresses NPC cell migration through the LRP6/GSK3β/β-catenin axis." (PMID 40001923, 2025).
neuroblastoma (1 paper, 2021). Neuroblastoma (NB) is the most common solid, extracranial childhood tumor. "Lipid raft disruption via induction of cholesterol efflux from the membrane with methyl-β-cyclodextrin significantly reduces Lrp6 phosphorylation in neuroblastoma cells, indicating that membrane order and integrity is essential for Lrp6 activity." (PMID 33585487, 2021).
neuroendocrine tumors (1 paper, 2024). "This retrospective study investigated the serum levels of LRP6, SFRP3, and DVL1 in patients with neuroendocrine tumors (NETs) and a control group using the ELISA method." (PMID 39796676, 2024). "The aim of this study was to evaluate and compare the serum concentrations of LRP6, SFRP3, and DVL1 between patients with neuroendocrine tumors (NETs) and healthy individuals, and to correlate these findings with selected demographic, clinicopathological, and biochemical characteristics." (PMID 39796676, 2024). "The lack of statistically significant differences in LRP6 concentrations, combined with limited research, underscores the need for further studies to understand its role in neuroendocrine tumors." (PMID 39796676, 2024).
pancreatic adenocarcinoma (1 paper, 2019). "Notably, the low-density lipoprotein receptor-related protein 6 (LRP6), an indispensable co-receptor for WNT, is frequently overexpressed in colorectal, liver, breast and pancreatic adenocarcinomas in association with increased WNT/β -catenin signaling." (PMID 31412666, 2019).
pancreatic neuroendocrine tumor (1 paper, 2024). Pancreatic endocrine tumor, also known as pancreatic neuroendocrine tumor (PNET), describes a group of endocrine tumors originating in the pancreas that are usually indolent and benign, but may have the potential to be malignant. "For example, in pancreatic neuroendocrine tumors (PNETs), dysregulated pathways involving LRP6 are associated with tumor growth and progression." (PMID 39796676, 2024).
periodontitis (1 paper, 2023). An acute or chronic inflammatory process that affects the tissues that surround and support the teeth. "During periodontitis, the expression levels of LRP6, β-catenin, and LEF1 were suppressed in the inflammatory microenvironment." (PMID 37244994, 2023).
preeclampsia (1 paper, 2021). Preeclampsia is a hypertensive disorder of pregnancy that is characterized by new-onset hypertension with proteinuria presenting after 20 weeks of gestation, and depending on mild or severe forms may initially present with severe headache, visual disturbances, and hyperreflexia. "Our study partially clarified the role of miR-513c-5p in the development of preeclampsia by regulating LRP6 and provided new suggestions for its specific diagnosis and treatment." (PMID 34930169, 2021).
prune belly syndrome (1 paper, 2018). "For example, Wntlss and β-catenin knockout manifesting in Prune belly syndrome and Wnt/β-catenin, Gsk-3b, Lrp5 and Lrp6 knockout causing ectopia cordis." (PMID 29483576, 2018).